TIMM8B (translocase of inner mitochondrial membrane 8 homolog B)
Description:
Probable mitochondrial intermembrane chaperone that participates in the import and insertion of some multi-pass transmembrane proteins into the mitochondrial inner membrane. Also required for the transfer of beta-barrel precursors from the TOM complex to the sorting and assembly machinery (SAM complex) of the outer membrane. Acts as a chaperone-like protein that protects the hydrophobic precursors from aggregation and guide them through the mitochondrial intermembrane space (By similarity).
Synonyms: DDP2; TIM8B; FLJ21744; MGC102866; MGC117373
Tractability: Antibody: UniProt places it where antibodies can reach, with medium confidence. PROTAC: ubiquitination databases record sites on it; its protein half-life has been measured.
Gene: Protein-coding gene on chromosome 11 (112,084,800 to 112,086,798, reverse strand). Ensembl gene ENSG00000150779.
Subcellular location: Mitochondrion inner membrane
Pathways (Reactome):
Protein localization: Mitochondrial protein import
Gene Ontology:
Molecular function: protein transporter activity; zinc ion binding
Biological process: protein insertion into mitochondrial inner membrane
Cellular component: extracellular region; mitochondrion; mitochondrial intermembrane space; mitochondrial intermembrane space chaperone complex; mitochondrial inner membrane
Genetic constraint (gnomAD): Loss-of-function variants: 5 observed, 6.6 expected, observed/expected ratio (o/e) 0.76, 90% interval 0.39 to 1.55. That is too few expected variants to judge how well the gene tolerates losing a copy. Missense variants: 104 observed, 103.94 expected, observed/expected ratio (o/e) 1, 90% interval 0.85 to 1.18. Synonymous variants: 44 observed, 37.38 expected, observed/expected ratio (o/e) 1.18, 90% interval 0.92 to 1.51.
Homologues: Orthologues: chimpanzee TIMM8B (100% identical), dog TIMM8B (100% identical), macaque TIMM8B (100% identical), pig TIMM8B (100% identical), rabbit TIMM8B (99% identical), guinea pig TIMM8B (98% identical), mouse Timm8b (98% identical), rat Timm8b (86% identical), tropical clawed frog timm8b (73% identical), zebrafish timm8b (67% identical), Drosophila melanogaster Tim8 (55% identical). Paralogues in human: TIMM8A (46% identical).
Diseases named in the same sentence as TIMM8B in open-access papers:
TIMM8B is named in the same sentence as 8 diseases in open-access papers, as found by Europe PMC text mining. Sharing a sentence is not in itself a finding about the gene and the disease. The quoted sentences say what the papers report.
colorectal cancer (1 paper, 2022). A primary or metastatic malignant neoplasm that affects the colon or rectum. "Mutation in TIMM8B occurred in only one subject with colorectal cancer (TMB of 52.14 mut/Mb and concurrent BRAF V600E mutation), and the patient died within one month of PD-1 inhibitor monotherapy." (PMID 36358851, 2022).
deafness (1 paper, 2015). An inherited or acquired condition characterized by the complete loss of the ability to hear from one or both ears. "This hypothesis is supported by our present data, especially by our transcriptome analysis as inherited deafness genes (such as COCH (coding for cochlin), TIMM8B, PRPS1 and tRNA synthetase) are downregulated in AK2-deficient cells." (PMID 26270350, 2015).
hypothyroidism (1 paper, 2023). Abnormally low levels of thyroid hormone. "In accordance with our results, TIMM8B was up-regulated in hypothyroidism and only in nonsurvivors patients." (PMID 37249456, 2023). "Furthermore, some mitGenes with a concordant expression gain related to ATP production mechanism were shared between hypothyroidism and sepsis: SLIRP and TIMM8B appeared in sepsis nonsurvivor scenarios; ROMO1 and BLOC1S1 were present in both survivor and nonsurvivor scenarios." (PMID 37249456, 2023).
nasopharyngeal carcinoma (1 paper, 2023). A carcinoma arising from the nasopharyngeal epithelium. "Furthermore, we screened five up-regulated lncRNAs (LOC100144603, RP11-545G3.1, SCARNA22, TAZ, and TIMM8B) and six down-regulated lncRNAs (AC003986.7, AK055386, BC013821, DQ786304, LOC647979 and RP11-179H18.2) in nasopharyngeal carcinoma specimens." (PMID 37710236, 2023). "Following the intersection of the results from the two datasets, we obtained five up-regulated lncRNAs (LOC100144603, RP11-545G3.1, SCARNA22, TAZ and TIMM8B) and six down-regulated lncRNAs (AC003986.7, AK055386, BC013821, DQ786304, LOC647979 and RP11-179H18.2) in nasopharyngeal carcinoma." (PMID 37710236, 2023).
Sepsis (1 paper, 2023). Sepsis is defined as life-threatening organ dysfunction caused by a dysregulated host response to infection. "Finally, we demonstrated that ROMO1, SLIRP and TIMM8B could be predictive biomarkers in children's sepsis." (PMID 37249456, 2023). "BLOC1S1, ROMO1, SLIRP and TIMM8B mitGenes showed the capability to distinguish sepsis survivors and nonsurvivors." (PMID 37249456, 2023). "In adult sepsis, BLOC1S1, ROMO1, SLIRP and TIMM8B showed excellent ability to identify nonsurvivor samples." (PMID 37249456, 2023).
tumor (1 paper, 2019). "Of them, > 40% were mitochondrial ribosomal proteins (MRPs) including MRPL18 and TIMM8B that we here report to be upregulated in diabetics both in the tumor and the mucosa." (PMID 31199051, 2019).
TIMM8B also shares sentences with these, for which no sentence is quoted: epidermoid carcinoma (1 paper); virus infection (1).